RNU4-91P (RNA, U4 small nuclear 91, pseudogene)
Gene: Small nuclear RNA gene on chromosome 3 (175,609,479 to 175,609,613, forward strand). Ensembl gene ENSG00000201648.
Homologues: Orthologues: chimpanzee U4 (96% identical), dog U4 (60% identical), dog U4 (59% identical), dog U4 (58% identical), dog U4 (56% identical), dog U4 (54% identical), guinea pig U4 (53% identical), mouse Gm24256 (48% identical), guinea pig U4 (47% identical), guinea pig U4 (46% identical), mouse Gm22479 (44% identical). Paralogues in human: RNU4-51P (62% identical), U4 (62% identical), RNU4-15P (61% identical), RNU4-53P (61% identical), RNU4-5P (61% identical), RNU4-59P (60% identical), RNU4-90P (60% identical), RNU4-40P (59% identical), RNU4-49P (59% identical), RNU4-10P (59% identical), RNU4-46P (59% identical), RNU4-4P (59% identical), and 81 more.